NES (nestin)
Diseases named in the same sentence as NES in open-access papers (continued):
Sharing a sentence is not in itself a finding about the gene and the disease.
tumor (continued). "Nestin impacts cell motility and EMT properties in PDAC cells and its knockdown in PDAC cells led to reduced tumor incidence and volume, as well as the formation of liver metastases in a murine PDAC model." (PMID 38398077, 2024). "Consistent with the in vitro analysis, the protein levels of Nestin and SOX2 were decreased in tumor tissues." (PMID 39501082, 2024). "Stable LIN28B downregulation resulted in a significant decrease in the tumor markers SOX2, NESTIN, and SOX9 and an increase in the neural differentiation marker GAP43, consistent with the critical role of LIN28B in maintaining stemness." (PMID 38732012, 2024). "Top differentially suppressed genes as the tumor transformed included SMOC1, BCAN, NES, AIF1L, ENC1, and IGF2 (p < 0.01)." (PMID 39256867, 2024). "Immunoistochemically, both benign and malignant tumor cells typically stain positively for S-100, CD68, neuron-specific enolase, CD57, inhibin, calretinin, TFE3, SOX10, and nestin." (PMID 39372871, 2024). "In GBM, KLF4 has been shown to activate Notch and its downstream target Nestin, thereby establishing proneural GSC identity and contributing to the survival of GSCs and tumor growth." (PMID 39273014, 2024). "Similar to NRAS(G12V)-N1ICD-driven tumours, early-onset tumours with DS3–4 were mostly positive for nestin and NOTCH1, whereas the majority of late-onset differentiated tumours (DS1–2) were negative for nestin/NOTCH1." (PMID 39112713, 2024). "This suggests that Nestin levels and CL3 signature expression are predictive indicators of tumor aggressiveness." (PMID 38684700, 2024). "Using immunohistochemistry staining, the tumor biopsies of mice injected with CEGBC-GB spheroids and CEGBC-DB spheroids displayed nestin-positive staining in the grafted hemisphere." (PMID 38553638, 2024). "Analysis of tumor spheres has revealed co-expression of ITGA6 with the tumor stem cell markers CD133, nestin, and Olig2." (PMID 39239559, 2024). "Mangiola and colleagues studied Nestin and JNK expression in the tumor and peritumoral area of GBM specifically." (PMID 36300592, 2023). "Tumors were diffusely infiltrative, and GFP+ tumor cells clearly colocalized with H3K27M and Ki-67 and expressed high levels of neural stem/progenitor cell markers OLIG2 and Nestin." (PMID 37011011, 2023). "Tacrolimus (FK506) has capacity to increase chemosensitivity of GSC and reduce GBM tumor volume and hypoxia-induced surface markers (ki67, GFAP and nestin) in GSC." (PMID 37174078, 2023). "High grade tumors have a higher Ki67 proliferation index indicative of more aggressive tumor growth and they tend to exhibit high immunoreactivity for stem cell markers such as CD133, Nestin, Sox2 and Olig2." (PMID 37920169, 2023). "In addition, the criteria for defining higher tumor expression of nestin or positivity of nestin were varying among the included studies, and a uniform definition has not been developed, which may also contribute to the heterogeneity among the included studies." (PMID 37485559, 2023). "In contrast to VM, presence of CD31 or CD34 in cells that co-expressed tumour markers (e.g. EGFR amplification) or stem cell markers (e.g. CD133, Nestin) indicated vessels containing endothelial cells resulting from transdifferentiation of GSCs." (PMID 36823554, 2023). "Remarkably, a population of nestin-/NG2+ and nestin+/NG2+ cells surrounding neoplastic cells was observed and these cells were also present between tumor cells." (PMID 37015965, 2023). "Based on these initial studies, a series of additional cell markers, including Nestin and SOX2, that show differences in tumor initiation and self-renewal have been validated." (PMID 36805592, 2023). "The tumor cells were stained positively for some neurogenic makers, for instance S100, Syn, MAP2, NFP, Nestin, CD56, and SOX2, which highlighted the neural lineage differentiation of tumor cells." (PMID 36153506, 2022).
tumor (continued). "The expression of CA9 was predominantly found in perinecrotic tumor cells, but the positive expression of HIF-1α, nestin, and FOXM1 was widely distributed." (PMID 35785200, 2022). "Significant correlations were seen for CD133 and Nanog between OPN in the primary and recurrent tumor and between CD133 and Nestin in recurrent tumors." (PMID 35183162, 2022). "Serial sections were used to spatially interrogate antigen expression of vimentin, VCAM-1, CD31, Ki67, nestin, and SOX2 in both tumor cells and the adjacent stroma, specifically at the tumor core, tumor rim, and contralateral striatum." (PMID 35312755, 2022). "Four patient tumor-derived neurospheres were generated and tested for the expression of stem cell markers CD133 and Nestin." (PMID 36299858, 2022). "Tumour-specific 18F-fluciclovine uptake on pre-clinical PET-CT corresponded to immunostaining for Ki-67, nestin and ASCT2." (PMID 35884545, 2022). "Immunostaining was performed to assess both proliferative/stem cell (Nestin, Sox2, Ki67, Vimentin, SSEA1, CD133) and quiescent (Cd9 and Gfap) markers within the tumours." (PMID 36420140, 2022). "In 3D-SFs, tumor cells enveloped the scaffold surface consisting of mostly GFAP+ cells and some Nestin+ cells." (PMID 35381525, 2022). "To further analyze the correlation between expression of cell markers (SOX2, SOX9, Nestin, and Ki67) and the proximity to the SVZ, we used the distance from centroid of tumor to SVZ." (PMID 35795469, 2022). "Multivariable linear regression was performed to ascertain the possible relation between distance from tumor centroid to SVZ and age, sex, and percentage of positive core cells of SOX2, SOX9, Nestin, and Ki67." (PMID 35795469, 2022). "Immunohistochemistry using various tumor stem cell-specific markers, including acetaldehyde dehydrogenase 1, CD44, CD133, Nestin, NGFR, and SOX9, revealed short spindle-positive cells scattered within the tumor, suggesting the involvement of tumor stem cells." (PMID 36187098, 2022). "With confocal laser scanning microscopy, we were able to detect clusters of tumor cells expressing both, CD133 and Nestin." (PMID 35183162, 2022). "To clarify the existence of GSCs outside the tumor front, we obtained biopsies from GBM patients in the immediate peri-tumor region and mapped the tumor stem-like cells with the markers Sox2, Nestin and CD105." (PMID 36038950, 2022). "Specifically, in magenta, a subset of neural crest progenitor markers, such as NES, SOX10, ERBB3, and NGFR, were reported as highly expressed markers of Schwann cell progenitors and the signatures of stem-like tumor cells in NF1 tumors." (PMID 35741605, 2022). "In the present study, “pseudo-papillary” structures containing nestin+/FOXM1+ cells in the perivascular niche and CA9/HIF-1α positivity in the area surrounding stem cell accumulation resembled co-opted tumor vessels and were observed in refractory-Bev." (PMID 35785200, 2022). "GSCs (both SU4 and SU5) had a strong ability to form tumor-sphere like cell clusters, and expressed GSCs markers, including CD133, nestin and CD44, consistent with the GSCs stemness characteristics." (PMID 33621205, 2021). "The expression of NANOG and OCT4 was evaluated by immunohistochemistry in 122 cases, SOX2 in 121 cases, Nestin in 93 cases and PDPN in 85 cases in which representative tumor tissue was available." (PMID 34201050, 2021). "Speaking to the essential role of GSC in tumor growth, ablating these Nestin + cells prevented tumor growth, and, with the addition of TMZ, it stopped tumor development altogether." (PMID 33805316, 2021). "Tumor cells demonstrate strong positive staining for vimentin, CD34, apolipoprotein D, and nestin when subjected to immunohistochemical studies." (PMID 33715634, 2021). "While several progenitor genes such as SOX2 and NES were expressed broadly, PROM1 (expressed as CD133), a marker that has been shown to be sufficient to give rise to ectopic tumours, was very sparsely expressed." (PMID 34948008, 2021).
tumor (continued). "RPS6-KD suppressed the tumor-sphere formation of GBM cells through the inhibition of p-JAK2 and p-STAT3 and concomitantly downregulated the stemness-related proteins Nestin and SOX2." (PMID 35008473, 2021). "Both the patient and the PDX tumours were positive for OLIG2, nestin, vimentin and GFAP, with focal Ki-67 proliferative indices of up to 25% in the patient tumour and 40% in PDX tumours, respectively." (PMID 33053751, 2020). "The microscopy of AG exhibited tumor cells arranged around vessels shaped like clumped chrysanthemums, and tumor cells were strongly and diffusely positive for GFAP and Nestin." (PMID 32058680, 2020). "As expected, tumor sphere formation assays determined that circPTN promoted increased levels of stemness markers, such as Nestin, CD133, SOX2, and SOX9, and tumor growth in vitro and in vivo, primarily via sponging miR-145-5p/miR-330-5p." (PMID 32528957, 2020). "Immunohistochemistry of tumor samples from an orthotopic mouse model by double staining of BPA and a stem marker (SOX2 or Nestin) or differentiation marker, GFAP, revealed that all SOX2- or Nestin-positive GSLCs were also positive for BPA." (PMID 33086625, 2020). "The nestin+ cells were distributed among LYVE‐1+ lymphatic endothelial cells, and many LYVE‐1+ nestin+ tumor cells were identified." (PMID 31960509, 2020). "We found that in the tumor and the tumor microenvironment, CCL2 and CXCL10 localized in Nestin+, Iba-1+, CD16+ and CD163+ cells." (PMID 32943658, 2020). "Cells that co-expressed Nestin and APELA mRNA were found in discrete regions throughout tumor tissue from three different GBM patients." (PMID 30917521, 2019). "The expression of the tumor glial marker GFAP and the neural marker Nestin were maintained in MNL and NS cultures for early passages, while long-term cell expansion partially lost the markers’ expression." (PMID 31779235, 2019). "In nestin-positive OSCC samples, both peripheral and central cells of the tumor islands showed positivity." (PMID 31675305, 2019). "Immunohistochemical examination of 10 distinct tumors showed that in most of the tumors, Tomato+ tumor cells express melanocytic markers Dct and MITF, neuronal markers Nestin, Tubb3 and Gfap, mesenchymal marker Pdgfra and proliferation marker Ki67." (PMID 31685822, 2019). "si-hVDAC1 tumor treatment markedly decreased the expression of CSCs markers, such as CD133, SOX2, KLF4, Nestin, and CD44, as evaluated by quantitative immunoblotting and qRT-PCR." (PMID 31661894, 2019). "Immunostaining of cryosections against the stem cell markers nestin, SOX2 and Oct4 suggested that the spheroids contained a population of stem-like tumor cells." (PMID 31227783, 2019). "CT and PVZ cells expressed neural tumor stem cell markers CD133, NESTIN, OLIG1, OLIG2, SOX2 and A2B5." (PMID 30333910, 2018). "This study showed that nestin+ cells had CSC-like properties, because they demonstrated the capacity of long-term tumour growth and mediated tumour relapse following therapy." (PMID 29991569, 2018). "Among the cell cultures from four tumor tissues, we obtained two SFCs (SFC-1 and SFC-2), both expressing stem cell markers CD133 and Nestin at almost the same levels." (PMID 30210550, 2018). "Compared to the original tumor, R2J cells in culture (2D and spheres) lost the GFAP and CD56 expressions (only 2D) whereas Ki67, vimentin and nestin expressions were conserved as well as mesenchymal shift markers, such as CD44." (PMID 30583471, 2018). "In vivo, the FK506/Vincristine treatment decreased the tumor size as well as ki67, Glial Fibrillary Acidic Protein (GFAP), and nestin expression." (PMID 30208561, 2018). "Original tumor, R2J, cultured in monolayer (2D) and in spheres showed a persistence expression of CD44, CD56 (except in monolayer), EGFR, Ki67, Nestin, and vimentin." (PMID 30583471, 2018).
tumor (continued). "We also verified the same pattern for nestin and GFAP for the cell lines when they formed tumor spheres." (PMID 28148893, 2017). "Correlations of the expression levels with the presence of aberrant vessels were analyzed by confocal laser microscopy analysis, using FVIII as endothelial cell marker, CD133 and nestin as CSC marker, CD20 as tumor cell marker, and Stat3." (PMID 28415725, 2017). "In the neoadjuvant group, as previously reported, improvement of tumor oxygenation was noted in eight of the nine tumors, and the MVD and nestin-positive cell ratio were significantly decreased compared with the pre-Bev initial tumors." (PMID 29262608, 2017). "Correlations of the expression levels with the presence of aberrant vessels were analyzed by confocal laser microscopy analysis, using FVIII as endothelial cell marker, CD133 and nestin as cancer stem cell (CSC) marker, CD20 as tumor cell marker, and Stat3." (PMID 28415725, 2017). "After immunohistochemistry, tumor vessels appeared lined by CD133+ and nestin+ cells and CD133+ and nestin+ tumor cells were detected near the vessels." (PMID 28415725, 2017). "After dual confocal immunofluorescence reactions, tumor vessels were lined by both CD133+ CSCs and FVIII+ endothelial cells, as well as nestin+ CSCs and FVIII+ cells, with merged colocalization fluorescence signals." (PMID 28415725, 2017). "The correlation between Nestin and EMT suggests possible involvement of Nestin in drug-resistance and tumor invasion." (PMID 27412382, 2016). "Immunofluorescence and FACS analysis showed that most of the cells in the tumor spheres were double positive on CD133 and Nestin." (PMID 26908439, 2016). "Nestin is frequently up-regulated in HCC, and has been previously shown to be significantly correlated with tumor angiogenesis and poor prognosis in HCC patients." (PMID 27412382, 2016). "The objectives of this study were to evaluate MVD with a focus on nestin, CD90-positive vessels and quantification of FOXP3+ Tregs in comparison to the numbers of CD3+ tumor infiltrating lymphocytes." (PMID 25913374, 2015). "These infiltrating tumor cells showed activation of EGFRvIII/STAT3 signaling and expression of stemness markers (Nestin and Sox2) in vivo." (PMID 25992628, 2015). "Complementary ex vivo experiments using explants of murine aortas revealed that Nestin(+) multipotent stem cells (MPSCs) are mobilized from their niche and differentiated into pericytes and SMC through the influence of tumor-cell-secreted factors." (PMID 25019063, 2014). "The flow cytometry analyses showed 92.1% cells expressing GFAP, a tumor glial marker, of which 52.5% double stained for CD133 and 71% cells expressing Nestin, an immature neural stem cell marker, of which 44.8% double stained for CD133." (PMID 24432012, 2014). "Nestin is also involved in regulating the Wnt effector; the CD44 gene, a known putative cancer stem cell marker involved in mediating tumor cell metastasis." (PMID 24625091, 2014). "Our previous study confirmed nestin expression in NSCLC tissue samples, which appeared to correlate with the newborn lymphatic duct induced by tumor cells." (PMID 24498263, 2014). "Upon irr, the majority of GBM cells lost their Nestin expression, whereas a large fraction of GBM cells near central tumor mass strongly upregulated the astrocytic differentiation marker GFAP." (PMID 24052948, 2013). "We observed under serum monolayer conditions, that nestin positive or nestin and SMA double positive rat stromal cells outgrew EGFR amplified tumor cells, while serum spheroid cultures preserved tumor cells with EGFR amplification." (PMID 24349039, 2013). "IL-1β/TGF-β-induced neurospheres display up-regulated expression of stemness factor genes (nestin, Bmi-1, Notch-2 and LIF), and increased invasiveness, drug resistance and tumor growth in vivo: hallmarks of GSCs." (PMID 22330721, 2012).
tumor (continued). "In the mouse xenografts, staining for both host nestin and SMA showed similar staining pattern, illuminating the vascular network in the tumor bed." (PMID 22539956, 2012). "Rat nestin and GFAP double-positive cells were more numerous in the tumor periphery, but were also found in the tumor core." (PMID 22539956, 2012). "We observed that host nestin-positive cells that originated in the SVZ ipsilateral to the tumor implant migrated towards the xenograft borders and deeper into the tumor regions." (PMID 22539956, 2012). "All the tumours showing the simultaneous overexpression of CAF-1/p60, PARP-1 and nestin, developed, during follow-up, recurrence and/or metastases or death." (PMID 22882088, 2012). "Importantly, Nestin is a commonly used marker for neuroepithelial malignancies and further understanding of mechanisms regulating its expression may provide therapeutic targets in neuroepithelial tumour cells." (PMID 21826226, 2011). "The biologic activity of the mTOR inhibitor temsirolimus is further confirmed by the upregulation of nestin seen in the patient's IGFR/mTOR resistant tumor, since temsirolimus down-modulates EWS-FLI1, which would be expected to upregulate nestin." (PMID 21494688, 2011). "Immunohistochemical probes were applied to detect p-mTOR (Ser2448), p-Akt (Ser473), p-ERK1/2 (Thr202/Tyr204), nestin, and p-STAT3 (Tyr 705) in the original and recurrent tumor." (PMID 21494688, 2011). "Previously, disseminated tumor cells of melanoma patients with metastatic disease have been shown to express stem cell markers CD133 and NESTIN." (PMID 20459772, 2010). "We have investigated the tumor forming potential of two GBM cell lines, U251 and U87, expressing different levels of GFAP and Nestin." (PMID 21304179, 2010). "At the protein level, organoids expressed both stem/progenitor markers (nestin, vimentin, SOX10) and chromaffin differentiation markers (synaptophysin, CD56), although expression of the latter was markedly reduced compared to primary tumor tissue." (PMID 41928881, 2026). "Notably, we found NES+ and SOX2+ tumor cells in closer proximity to PDGFRβ+ regions, in comparison to MAP2+ cells." (PMID 40562749, 2025). "Although these models captured the dual neuronal and oligodendroglial features of NB-FOXR2 tumors, the lack of neuronal subtype specificity and locations of tumor formation likely reflects the broad targeting of Nestin+ progenitors." (PMID 39495206, 2025). "Second, the interpretation of the co-expression of PSMA with the tumour-cell marker nestin was hampered by the fact that nestin itself was not expressed in all tumour cells." (PMID 40414994, 2025). "Given that the GSC state is not a stable clonal subpopulation but rather a plastic state induced by the tumor microenvironment, we scored cells based on classic GSC markers (PROM1, SOX2, NES, OLIG2, BMI1, NANOG, POU5F1) and defined the top 2% of cancer cells with the highest stemness scores as GSCs." (PMID 41041071, 2025). "Of particular interest is the presence of NESTIN as NESTIN+ (but not NESTIN-) pericytes were recruited to the blood vessels during tumor angiogenesis in the murine intracerebral glioblastoma." (PMID 38509074, 2024). "These tumor biopsies had not undergone pre-examination by a neuropathologist to confirm Nestin expression." (PMID 39039193, 2024). "In non-treated mice, Nestin, a marker of neuro-epithelial stem cells not expressed in mature neurons, but expressed in activated astroglial cells and tumor cells, exhibited strong expression in GL261 parental tumors and in peritumoral astrocytes (vehicle; Nestin)." (PMID 39334370, 2024). "This ensured that expression of ICP34.5 was spatially confined to specifically GBM tumours which exhibit high expression of nestin and not in normal brain tissues where nestin is not expressed." (PMID 38615034, 2024).